INS (insulin)
Diseases named in the same sentence as INS in open-access papers (continued):
Sharing a sentence is not in itself a finding about the gene and the disease.
diabetes (continued). "Accordingly, glyburide improved diabetes control (HbA1c on insulin:52 mmol/mol/6.9%; on glyburide:36 mmol/mol/5.4%) and also performance on motor coordination tests that were impaired before the switch of therapy." (PMID 23667671, 2013). "NOD mice with prediabetic stages of diabetes can be protected from diabetes after immunization with the 9–23 amino acid region of the insulin B chain (B:9–23) in IFA." (PMID 23970886, 2013). "Diabetes research and product development have long been focused on the reverse or improvement of diabetic conditions through enhancing insulin secretion and/or improving peripheral insulin sensitivity." (PMID 24167617, 2013). "Hypoglycemia is one of the main limiting factors for patients with diabetes requiring insulin in achieving tight glycemic control and reduced rates of complications." (PMID 23737776, 2013). "Most participants (99%) with diabetes self-reported their diabetes status through a tick box response; the remainder wrote diabetes in free text field (n = 119) or reported insulin use (n = 58)." (PMID 24245780, 2013). "At baseline of 24,151 participants in the 45 and Up Study assigned to the diabetes group, 10% (n = 2,379) self-reported using insulin and 58% (n = 13,962) self-reported OHAs." (PMID 24245780, 2013). "The increasing degree of insulin resistance in quartiles of HOMA-IR is associated with a progressive increase in body mass index, level of insulin and fasting glucose, as well as the frequency of positive family history of diabetes." (PMID 23819910, 2013). "We present a 42-year-old female patient with a 7-year history of diabetes on insulin therapy, referred to our clinic with a 3-year history of multiple asymptomatic firm plaques disseminated on the upper and lower extremities." (PMID 23533835, 2013). "Glucotoxicity, which deteriorates functions of insulin on peripheral tissues and the secretion of insulin by beta cells is a critical factor of the pathophysiology of diabetes mellitus." (PMID 24039692, 2013). "In the Diabetes Mellitus Insulin Glucose Infusion in Acute Myocardial Infarction 2 (DIGAMI 2) trial glucose-insulin infusion failed to result in a survival benefit however." (PMID 23574917, 2013). "The drugs that are currently available in the treatment of diabetes are mainly targeted either to improve insulin sensitivity or improve insulin secretion or both." (PMID 24319481, 2013). "Costs for glucose self-monitoring were the main cost category (28.5%), followed by costs for continuous subcutaneous insulin infusion (25.0%), diabetes-related hospitalizations (22.1%) and insulin (18.4%)." (PMID 23967077, 2013). "Thiamine treatment did not improve the hearing problem in any of our patients, but improved diabetes in P-1 after 2 months and therefore insulin was stopped." (PMID 23454484, 2013). "Increased attention should be paid to patients who are younger, patients who have had longer diabetes history, patients who are on insulin therapy and patients who are less compliant to medication treatment." (PMID 23725198, 2013). "Mg has received considerable attention for its potential in improving insulin sensitivity and preventing diabetes and its cardiovascular complications." (PMID 23418599, 2013). "As a result, recurrent and unnoticed cycles of potentially dangerous hypoglycaemia can ensue, particularly in the case of insulin-requiring diabetes." (PMID 24053606, 2013). "The same team of specialty nurses and a dietitian provides diabetes education and insulin management training to the parents and child and covers the same content regardless of education setting (i.e. hospital and/or outpatient pediatric endocrinology clinic)." (PMID 23587308, 2013). "The position of these molecules seems to be most significant as they are a subset of commercially employed non-insulin-dependent diabetes mellitus and insulin-sensitizing agents such as rosiglitazone, epalrestat, ciglitazone, AD-5061, pioglitazone, and so on." (PMID 23458122, 2013).
diabetes (continued). "Diabetes mellitus is a complex metabolic disorder resulting from either insulin insufficiency or insulin dysfunction." (PMID 24093976, 2013). "In our study, patients using OADs plus insulin therapy had a longer history of diabetes than patients using OADs alone." (PMID 23800082, 2013). "Utility is greatest after 3–5 years from diagnosis when persistence of substantial insulin secretion suggests Type 2 or monogenic diabetes." (PMID 23413806, 2013). "One of the decisive reasons for the progression of diabetes mellitus is glucoliptoxicity that is induced by inadequate secretion of insulin from β-cells of pancreatic islets and/or by the impairment of glucose uptake in peripheral tissues." (PMID 23409091, 2013). "Diabetes therapy was dietary only in 33.5% of the patients, metformin in 56.0%, and insulin therapy in 22.9%." (PMID 24330386, 2013). "In our study, increased myostatin expression is inversely related to insulin sensitivity in diabetes." (PMID 24454989, 2013). "Overall, the most significant determinants of poor HRQoL are insulin use, obesity and diabetes related complications." (PMID 24349036, 2013). "Both insulin sensitivity and secretion are important in the pathogenesis of diabetes and prediabetes." (PMID 23671610, 2013). "Insulin injections subsequent to induction of toxin-induced diabetes significantly preserved β-cells and islet morphology." (PMID 23762878, 2013). "Protein-tyrosine phosphatase 1B (PTP1B) is a physiological regulator of insulin signaling and adiposity and is a drug target for the treatment of obesity and diabetes." (PMID 23937695, 2013). "I become more careful with food intake and do more exercise” (5 years of insulin use/ 2 years of having diabetes)." (PMID 24164794, 2013). "First, with increasing values of RDW, there is an increase in the rate of patients with serious comorbidities such as COPD, PVD, diabetes treated with insulin, atrial fibrillation and heart failure in the entire population." (PMID 24320974, 2013). "In spite of different study periods, these findings were consistent with our results concerning persons with non-insulin-treated diabetes who normally form the main part of the population with diabetes." (PMID 23837500, 2013). "At the time of the last follow-up examination, all of the latter subgroup had suffered from diabetes treated with insulin for at least 5 years." (PMID 24151618, 2013). "Most older patients with diabetes have Type 2 diabetes, which is typically a disease where endogenous insulin persists." (PMID 23659458, 2013). "Type 1 diabetes mellitus (T1DM) is characterized by the autoimmune destruction of insulin-producing pancreatic islet beta cells in genetically susceptible individuals, resulting in the total lack of insulin." (PMID 24228182, 2013). "Few females (6 out of 20 females) developed overt diabetes that requires insulin therapy and were excluded from this study." (PMID 23691181, 2013). "Leptin is decreased in low insulin states, such as experimentally induced diabetes, and increases after insulin treatment." (PMID 24455420, 2013). "Because all diabetic patients were treated with oral anti-diabetic medications or insulin at entry, the chance of misclassification of diabetes was actually very low." (PMID 23286275, 2013). "The CPE KO mouse develops diabetes, obesity and is infertile due to a defect in the production of peptide hormones such as insulin, α-melanocortin stimulating hormone and gonadotropin releasing hormone, respectively." (PMID 23554999, 2013). "In Asian patients, diabetes develops at a younger age and is characterized by early β cell dysfunction in the setting of insulin resistance, with many requiring early insulin treatment." (PMID 23551121, 2013).
diabetes (continued). "When oral hyperglycaemic treatments are contraindicated or cease to be effective in patients with diabetes mellitus type 2, exogenous insulin is given by intramuscular injection." (PMID 23983688, 2013). "Patients with diabetes who take insulin face many unique challenges related to travel to include dehydration and hypoglycemia." (PMID 24360506, 2013). "Targeted disruption of the Dicer1 gene specifically in β-cells leads to progressive reduction in insulin secretion and glucose tolerance and development of diabetes." (PMID 23878802, 2013). "Early use of insulin in the management of poorly controlled diabetes has been recommended to prevent and reduce the long-term diabetes complications." (PMID 24164794, 2013). "STZ-induced diabetic rats are one of the animal models of human insulin-dependent diabetes mellitus; these rats are characterized by high fasting blood glucose levels and drastic reduction in blood insulin concentration." (PMID 24090482, 2013). "These two groups were similar in age, duration of diabetes, time to insulin from diagnosis, and BMI." (PMID 23659458, 2013). "There was a large number of pateints on insulin pumps, suggesting a higher level of sophisticated diabetes care." (PMID 24156395, 2013). "Type 2 diabetes (T2D) is a heterogeneous disorder usually associated with insulin resistance and hyperinsulinemia leading to impaired glucose tolerance or frank diabetes as pancreatic insulin response declines." (PMID 23437106, 2013). "A large body of evidence has shown that decreased nuclear levels of Pdx1, Mafa or Neurod1 lead to dedifferentiation of beta-cells and consequently inadequate insulin secretion in diabetes." (PMID 23424659, 2013). "Diabetes mellitus is a metabolic disorder involving oxidative stress, which induces insulin resistance in the peripheral tissues and impairs insulin secretion by pancreatic β-cells." (PMID 23684219, 2013). "Although youth treated with SGAs seldom develop diabetes because of their large insulin reserve, they often develop insulin resistance and dyslipidemia, which markedly enhance the risk for long-term morbidity and mortality." (PMID 23947389, 2013). "As a complex metabolic disorder diabetes mellitus is characterized by chronic hyperglycemia due to defects in insulin secretion or insulin resistance." (PMID 23717693, 2013). "We recently demonstrated that adult OB and HPC NSCs collected from diabetic rats are useful cell sources for autologous cell transplantation to treat diabetes because they retain the intrinsic ability to produce insulin in the adult CNS." (PMID 23673084, 2013). "This study aims to evaluate the effect of an intervention with GSD-Y in groups of adolescents starting on insulin pumps and their parents on diabetes-related family conflicts, perceived health and quality of life (QoL), and metabolic control." (PMID 24354899, 2013). "IUGR increases the risk of type 2 diabetes mellitus (T2DM) in later life, due to reduced insulin sensitivity and impaired adaptation of insulin secretion." (PMID 23424667, 2013). "Insulin relies on endothelium-dependent vasodilation to enhance perfusion, thus endothelial dysfunction reduces insulin-mediated increases in muscle perfusion, which can contribute to the metabolic deficit in diabetes." (PMID 24772374, 2013). "The family history revealed that a maternal uncle was suffering from diabetes mellitus since the age of 31 years old, treated initially with oral hypoglycemic drugs and later with insulin." (PMID 24124913, 2013). "The first group (Type I) is often used to describe the onset of diabetes, which is triggered by the inability of the pancreas to produce sufficient amounts of insulin for glucose uptake and metabolism." (PMID 24324517, 2013). "Insulin need was higher in the NPHg either as total daily insulin in both types of diabetes or as rapid-acting analogue in type 2 diabetic women only." (PMID 23840206, 2013).
diabetes (continued). "The average duration of having diabetes was 8 years and the average duration of insulin use was 3.2 years." (PMID 24164794, 2013). "This remarkable improvement in diabetes with weight loss, following LAGB surgery is related to the double effect of improved insulin sensitivity and pancreatic beta-cell function." (PMID 23450466, 2013). "Circulating Fibroblast Growth Factor 21 (FGF21) levels are increased in insulin resistant states such as obesity, type 2 diabetes mellitus and gestational diabetes mellitus (GDM)." (PMID 23755203, 2013). "Several studies have compared the contribution of insulin secretion and resistance in the pathogenesis of diabetes in East Asians." (PMID 23551121, 2013). "Currently, the available therapies for diabetes include insulin and a variety of oral antihypoglycemic agents such as thiazolidinediones, sulfonylureas, and α-glucosidase inhibitors." (PMID 24204387, 2013). "Diabetes mellitus is a chronic multisystem disease related to abnormal insulin production, impaired insulin utilization, or both." (PMID 23985123, 2013). "Systemic vascular improvement can also improve insulin sensitivity, so targeting the endothelium in diabetes is a valid option for treating metabolic disease." (PMID 24772374, 2013). "Currently there are only two FDA approved therapies for pediatric patients with Type 2 diabetes mellitus: metformin and insulin." (PMID 24222881, 2013). "It is expected that the regulation of GLUT4 and insulin can likely be attributed to the anti-diabetes activity of BNR17." (PMID 23382926, 2013). "Type 2 diabetes mellitus (T2DM) describes a group of metabolic disorders characterized by defects in insulin secretion and insulin sensitivity." (PMID 23349838, 2013). "Exendin 4 reversed diabetes and increased insulin content together with restoration of NKp46 ligand expression." (PMID 24009765, 2013). "The usual treatment for type 2 diabetes mellitus includes life style modification, exercise, diet therapy, oral antihyperglycemic drugs, and insulin." (PMID 23983807, 2013). "Since PPARγ2 is expressed mainly in adipose tissue, a moderate reduction of its activity influences the sensitivity to insulin, diabetes, and other metabolic parameters." (PMID 23983677, 2013). "Diabetes mellitus is a disease in which the homeostasis of carbohydrate, protein and lipid metabolism is improperly regulated by insulin, resulting in elevated fasting and post-prandial blood glucose concentrations." (PMID 23684219, 2013). "Diabetes can be divided into 3 main types: Type 1 diabetes, which results from the inability to produce insulin; Type 2 diabetes, resulting from insulin resistance; and gestational diabetes." (PMID 23844373, 2013). "The progression from the NGR via IGM to DM2h to overt diabetes was considered due to the deterioration of insulin secretion and increasing of insulin insensitivity." (PMID 23876034, 2013). "In the present study, we compared the effect of diabetes on neurogenesis and insulin expression in adult NSCs." (PMID 23673084, 2013). "High levels of the adipocytokine adiponectin reflect low BMI as well as high insulin sensitivity in healthy subjects and patients with type 2 diabetes mellitus (DM)." (PMID 24083942, 2013). "Several epidemiological studies have in recent years shown a relationship between vitamin D and diabetes, the metabolic syndrome, insulin resistance, and some studies also with insulin secretion." (PMID 24391858, 2013). "In summary, the classification of diabetes using insulin secretion evaluation and immunological markers, which seems to be the most effective scheme, allowed us to distinguish 4 subgroups of patients." (PMID 23710177, 2013). "Diabetes duration, prolonged poor glycemic control, and the resulting need for insulin therapy are the main predictors of retinopathy in patients with type 2 diabetes." (PMID 24363502, 2013).
diabetes (continued). "Our proband represents the first PND case with heterozygous INS mutation that occurred within the HCR of PI SP and resulted in an early onset of diabetes." (PMID 23350652, 2013). "Innovative strategies for diabetes therapy aim to replace lost insulin-producing beta cells by reprogramming other cell types or by deriving beta cells from pluripotent cells." (PMID 23382704, 2013). "Our results demonstrated that the plasma glucose levels in diabetic rats decreased gradually while the insulin and C-peptide levels increased gradually although still, within the diabetic range until 4 months after induction of diabetes." (PMID 24279645, 2013). "The most prescribed non-insulin diabetes medication was metformin, with 58.9% of type 2 patients continuing therapy post-CSII." (PMID 27536441, 2013). "Effect of high-dose insulin analog initiation therapy was evaluated on lipid peroxidation and oxidative stress markers in type 2 diabetes mellitus (T2DM)." (PMID 23577222, 2013). "Increased insulin secretion correlates to increased diabetes development and first-degree relatives to T1D patients have increased levels of insulin in the blood." (PMID 23785500, 2013). "Six weeks after diabetes, verification animals were divided into four groups as follows: diabetic treated with insulin (3–5 U), diabetic treated with vitamin C (80 mg/kg), and diabetic and control groups." (PMID 25938109, 2013). "Diabetes is a complicated metabolic disorder which is characterized by a disturbance in the homeostasis between the control of glucose levels and insulin sensitivity." (PMID 24223745, 2013). "Diabetes mellitus is characterized by hyperglycemia that involves abnormalities in both insulin secretion and action at peripheral tissues, resulting in reducing insulin sensistivity at skeletal muscle, adipose and liver tissue." (PMID 23455665, 2013). "An unhealthy lifestyle including a high fat diet (HFD) has become common in Western societies and contributes to obese, insulin resistant states such as pre-diabetes, which if left untreated, can progress to Type 2 Diabetes Mellitus (T2DM)." (PMID 23951235, 2013). "“When the doctor advised me to start on insulin, the explanation was clear” (2 years of insulin use/ 5 years of having diabetes)." (PMID 24164794, 2013). "Diabetes mellitus is a group of metabolic diseases characterized by hyperglycemia resulting from defects in insulin secretion and insulin action or both." (PMID 26317014, 2013). "In animal models, SOCS proteins 1 and 3 have been shown to play a role in insulin signaling and diabetes; however, less is known about other members of the SOCS family and their role in the development of diabetes." (PMID 23767996, 2013). "Therapeutic potential of the combination of BDNF with the drug enhancing insulin secretion against diabetes should be investigated in future study." (PMID 24106476, 2013). "This was followed by a gradual increase in the mean plasma insulin levels which increased significantly after 4 months (1.12 ± 0.26 μg/L) and reached almost normal levels 10 months after the onset of diabetes (5 ± 0.6 μg/L)." (PMID 24279645, 2013). "They occasionally administered insulin injections to the persons with diabetes, and from time to time they performed blood glucose measurements on behalf of the persons with diabetes." (PMID 24455251, 2013). "Glibenclamide, a standard hypoglycemic drug, has been widely used for many years to treat diabetes by promoting insulin secretion through blockade of ATP-dependent potassium channels in the pancreatic β-cells." (PMID 24090482, 2013). "Two months after the induction of both types of diabetes, the level of blood biochemical factors (glucose, insulin, cortisol, triglycerides, cholesterol, LDL, and HDL) were measured." (PMID 23497689, 2013).